MTOR (mechanistic target of rapamycin kinase)
Diseases named in the same sentence as MTOR in open-access papers (continued):
Sharing a sentence is not in itself a finding about the gene and the disease.
cancer (continued). "The association between CERS1 and the PI3K/AKT/mTOR signaling pathway in our study is a newly found and important supplement to the mechanism of CERS1 in malignant tumors." (PMID 37046655, 2023). "MTOR rs2295080 was less common in PTC, and it was associated with a lower risk of developing cancer and a reduced risk of higher tumor stages." (PMID 36980552, 2023). "Aberrant activation of the PI3K/AKT/mTOR pathway strongly contributed to the malignant transformation of various cancers, including PDAC." (PMID 37239355, 2023). "It has been demonstrated in several studies that resveratrol inhibits glycolysis through the PI3K/Akt/mTOR signaling pathway in human cancer cells." (PMID 38136176, 2023). "Cepharanthine can induce autophagy and apoptosis in cancer cells by regulating the Akt/mTOR or AMPK/mTOR signaling pathways." (PMID 37446681, 2023). "A key role in this cancer is played by the PI3K/AKT/mTOR signaling pathway, which regulates cancer cell survival, invasion and apoptosis." (PMID 37509496, 2023). "The dysregulation of the PI3K/AKT/mTOR signaling pathway occurs most frequently in cancer patients and plays a critical role in driving tumor initiation and progression, as well as therapy response." (PMID 37056344, 2023). "The mechanistic target of rapamycin (mTOR) pathway is highly conserved between species and has been demonstrated to have an important role in cell growth, cancer, and immunity, including in the neutrophil inflammatory response." (PMID 36326284, 2023). "It has been reported that targeting leucine in cancer treatment is effective because leucine can activate the mTOR signaling pathway in intestinal epithelial cells, which plays a role in T cell activation." (PMID 36985120, 2023). "The PI3K/AKT/mTOR signaling pathway is traditionally involved in cellular functions, such as cell growth, proliferation, differentiation, motility, survival, and cancer." (PMID 37109772, 2023). "Activated Akt phosphorylates tuberous sclerosis complex 2 (TSC2) and relieves its inhibitory effect on mTOR, leading to mTOR activation and increased synthesis of multiple oncogenic proteins to promote cancer progression." (PMID 37190158, 2023). "Several studies have reported that PIK3CA and PTEN are the two most frequently altered genes of the PI3K/Akt/mTOR pathway in human cancers such as colorectal and breast cancer." (PMID 37900167, 2023). "YY1 also promotes PVT1 expression via binding to its promoter to further affect autophagy through the mTOR pathway, leading to increased invasion and adhesion activity in cancer." (PMID 37724907, 2023). "It downregulates multiple signaling pathways, such as NF-κB and PI3K/AKT/mTOR, and decreases the expression of downstream cancer genes, including antiapoptotic genes, VEGF, c-met, cyclins, Cdks, and proinflammatory cytokines." (PMID 36835162, 2023). "By inhibiting PI3K/AKT, Amy disrupts the pathway that would normally activate mTOR, meaning that mTOR is unable to activate the downstream processes that would lead to cancer progression." (PMID 37726740, 2023). "Total mTOR expression was significantly higher in cPTC relative to the other carcinoma histotypes, and the levels of phosphorylated mTOR in cPTC were significantly higher than in the FVPTC and cPTC metastases." (PMID 36980552, 2023). "RICTOR, through cellular signaling downstream of receptor tyrosine kinase (PI3K/AKT/mTOR), is actively involved in cytoskeleton assembly, cancer invasion processes, proliferation, metastasis and poor prognosis." (PMID 36231068, 2022). "This study also critically analyzed the effect of apigenin on cancer cell signaling pathways including the PI3K/AKT/MTOR, JAK/STAT, NF-κB and ERK/MAPK pathways." (PMID 35807549, 2022). "Pharmacological mTOR inhibitors are clinically applied for immunosuppressing after organ transplantation, cancer chemotherapy, as well as treating some neurological and psychiatric disorders in clinical trials." (PMID 36045116, 2022).
cancer (continued). "Metformin is an inhibitor of complex I in oxidative phosphorylation and also influences the PI3K/AKT mTOR pathway, which are both interesting targets in cancer therapy." (PMID 35814409, 2022). "PI3K, AKT, and mTOR are the three major nodes that suffer dysregulation and induce cancer progression." (PMID 36077529, 2022). "Excessive activity in the PI3K/AKT/mTOR signaling pathway, one of the most common hallmarks in human cancers, is an important therapeutic target for cancer treatment." (PMID 35328346, 2022). "mTOR is often dysregulated in human cancers, and somatic mutations that induce mTOR activation have recently been identified in several types of human cancers, suggesting that mTOR is a therapeutic target." (PMID 36110206, 2022). "The PI3K/AKT/mTOR pathway plays a major role in human cancers, being involved in the regulation of critical processes such as cell cycle, proliferation, metastatic progression and resistance to antitumor treatments." (PMID 35761360, 2022). "PI3K/AKT/mTOR pathway, involved in a variety of cellular functions, is known to contribute in oncogenesis and cancer progression influencing cell cycle, metabolism, migration and cell death." (PMID 33245508, 2022). "MIF is reported to be an upstream regulator of the mTOR signaling pathway, and the mTOR pathway is now considered a target for cancer therapy." (PMID 35280512, 2022). "Control of protein translation is known to be one of the critical proliferation pathways mediated by mTOR signaling in cancer cells." (PMID 36259537, 2022). "The mTOR pathway is a frequently activated pathway in human cancers, representing an attractive target for anti-cancer drug development." (PMID 35563174, 2022). "Rapamycin, another antifungal drug extracted from Streptomyces hygroscopicus, is currently considered as a potent immunosuppressant in clinical and a target for mTOR, a serine/threonine protein kinase, exerting cytotoxicity against various kinds of cancers." (PMID 35517785, 2022). "In comparison, everolimus, an mTOR inhibitor that directly targets cancer cells, inhibited MDA-B02-Luc cell survival in both conditions at low micromolar concentrations." (PMID 36293074, 2022). "Remarkably, we identified mTOR, BLM, MET, AMPK, and p130 as new SMYD3 interactors implicated in cancer processes." (PMID 35495117, 2022). "The role of mTOR (mammalian target of rapamycin) signaling has been well documented in cancer development including HCC." (PMID 35255005, 2022). "Because of the strong association in cancer, studies are being carried out to develop the inhibitors of PI3K/mTOR to treat different types of cancer." (PMID 36109789, 2022). "Their aberrant expression has been shown to play an important role in many cancer-related signaling molecules/pathways, such as Notch, mTOR, NF-kb, and the Wnt/β-catenin pathway, and can affect various malignant phenotypes in cancer cells." (PMID 36531231, 2022). "The PI3K/Akt/mTOR pathway is also an important signalling pathway in the regulation of the cell cycle, promoting tumour cell survival and proliferation in many cancers." (PMID 35529172, 2022). "The mTOR pathway is a critical pathway in cancer cell survival, proliferation and invasion and inhibition of mTOR activity has been shown to lead to decreased MM cell survival." (PMID 35757005, 2022). "mTOR is at the crossroad of many of these signaling networks that regulate the physical phenotype of cancer cells and transmit extracellular mechanical signals." (PMID 35163745, 2022). "ECHS1 oxidizes fatty acids (FAs) and branched-chain amino acids (BCAAs), which removes their activation of mammalian target of rapamycin (mTOR) signaling, a well-established factor that drives increased protein synthesis and mitochondrial biogenesis in cancer." (PMID 35281109, 2022). "A deeper understanding of this molecular process will explain the reported beneficial effect of mTOR targeting in cancer therapy." (PMID 35159342, 2022).
cancer (continued). "The PI3K/AKT/mTOR signaling pathway is important for cell proliferation and survival, and abnormal activation of PI3K/mTOR signals is commonly found in cancer." (PMID 35205716, 2022). "Given that hyperactive mTOR often leads to the dysregulation of protein synthesis, targeting cap-dependent translation is therefore an attractive cancer therapy." (PMID 35805935, 2022). "Our study in senescence-like cancer cells showed that in AA-rich medium all GTPases were required for optimal mTOR activity." (PMID 36267578, 2022). "The mammalian target of rapamycin (mTOR) pathway is dysregulated in many cancer cells and plays a key role in mitochondrial metabolism regulation." (PMID 36382559, 2022). "The significant contribution of the PI3K/AKT/mTOR signaling pathway in the progression of GC suggests that this signal axis is a promising target for cancer therapy." (PMID 36209270, 2022). "mTOR signalling positively regulates cell proliferation and tumorigenesis in various cancers and is often aberrantly activated in cancer." (PMID 36081994, 2022). "SGK1 is a crucial Akt‐independent regulator of the PI3K/mTOR signaling pathway which is involved in the regulation of cancer growth, survival, metastasis, autophagy, immunomodulation, cancer stem cells, cell cycle, and induction of therapeutic resistance." (PMID 35106936, 2022). "That glutamine was taken up in exchange for essential amino acids (EAA) is the rate-limiting step in mTOR activation of cancer cells." (PMID 36203437, 2022). "The mammalian target of rapamycin (mTOR) pathway is central to the development of multiple cancers, including UC." (PMID 35864526, 2022). "Akt and mTOR are aberrantly activated in cancers and targeting these proteins are interesting for cancer drug discovery." (PMID 36180880, 2022). "AMPK is activated through the tumor suppressor liver kinase B1, resulting in inhibition of the mammalian target of rapamycin pathway (mTOR), activated in many human cancers." (PMID 35327549, 2022). "A recent study has demonstrated that ER stress can regulate the mTOR signaling pathway to exert anti-cancer effect." (PMID 35620287, 2022). "Since the development of sirolimus occurred more than 30 years ago, much has been learnt about the significance of mTOR in cellular process coordination and its relevance in cancer." (PMID 36109789, 2022). "DDIT4 activity supposedly enhances cancer cell resistance to mTOR inhibitors, thereby increasing cancer cells chemoresistance." (PMID 35659359, 2022). "Fucoxanthin suppresses cell proliferation via cancer cell signaling pathways such as Akt/mTOR/S6 kinase signaling pathway in ovarian cancer cells." (PMID 36555740, 2022). "mTOR regulates the translation of ribosomal proteins and promotes cancer initiation and metastases while MYC activation specifically regulates the translation of the mitochondrial respiration complex to support aggressive tumor growth." (PMID 35626002, 2022). "The first aspect is the elimination of cancer cell malignant features through SMC induced inhibition of PI3K/Akt/mTOR signaling pathway axis." (PMID 35343115, 2022). "A careful examination of some cell functions influenced by mTOR-targeting HOTAIR is warranted to provide more evidence for their impacts on cancer cells in the future." (PMID 36230902, 2022). "The mTOR pathway is frequently dysregulated in human cancers, rewiring cancer cell metabolism and the tumor microenvironment to promote tumor progression." (PMID 36479072, 2022).
cancer (continued). "At the protein level, the expression levels of EGFR, HSP90AA1, and mTOR were significantly different between normal and cancer tissues (all p < 0.05)." (PMID 36569844, 2022). "First, we are yet to functionally link the CAMKK2-mediated changes in circulating insulin levels to the observed changes in cancer cell size, mTOR signaling, and cancer progression." (PMID 35741020, 2022). "Among cell-non autonomous mechanisms that limit the efficacy of mTOR inhibitors in cancer therapy are potential immunosuppressive effects." (PMID 36077374, 2022). "In this study, we recommended 71 mTOR-inhibitor-based therapies for pretreated cancer patients primarily based on the strong activation of the mTOR pathway." (PMID 35454843, 2022). "PI3K/AKT/mTOR inhibitors also influence the antitumor effects of tumor immune cells infiltrating in cancers." (PMID 36313041, 2022). "The prominent role of the PI3K/AKT/mTOR pathway in endometrial tumorigenesis makes it an ideal therapeutic target for this type of cancer." (PMID 35408777, 2022). "Of note, combining antagonists of PTEN and mTOR reduces cancer cell proliferation and improves clinical outcomes in 50% of glioblastoma patients." (PMID 35242705, 2022). "Crosstalk between RAS/MAPK and PI3K AKT/mTOR pathways has been shown to promote treatment-resistant growth in many cancers." (PMID 35158750, 2022). "The authors found that fluphenazine is able to induce autophagy through mTOR inhibition and suggested this drug as a promising candidate for autophagy modulation in cancer." (PMID 36291568, 2022). "Cancer is characterised by an aberrant mTOR signalling that supports tumour proliferation, survival, metabolic programming, and drug resistance." (PMID 36577970, 2022). "One of the potential mechanisms of growth-limiting conditions that drive cancer progression is mTOR-dependent cellular senescence." (PMID 35533376, 2022). "The abnormal activation of the PI3K/AKT/mTOR pathway contributes to the malignant characteristic of cancer cells, including acquired autonomic growth signal, apoptosis resistance, angiogenesis, metastasis enhancement, and anti-growth signal insensitivity." (PMID 36349192, 2022). "In view of all this information, it remains vital to study mTOR more thoroughly because its participation in cancer metabolism is undeniable, which is why it seems to be such an important research direction." (PMID 36574435, 2022). "The use of phosphoinositide-3-kinase (PI3K) and mTOR inhibitors represent a promising approach in cancer therapy." (PMID 35010124, 2022). "The PI3K/AKT/mTOR signaling pathway is a key signal transduction pathway involved in the many hallmarks of cancer, including survival, metabolism, motility, and genome stability." (PMID 35807290, 2022). "In this analysis, we examined the efficacy, feasibility, and limitations of the application of mTOR inhibitors based on the individual molecular profiles of pretreated cancer patients after the failure of all standard treatments in the palliative setting." (PMID 35454843, 2022). "The involvement of KRAS in glucose and the energy metabolism of cancer cells is well established and there is growing evidence linking mutations in KRAS and aberrant PI3K/AKT/mTOR pathway activity." (PMID 36497428, 2022). "RHEB functions as a major upstream activator of the mTOR pathway, which promotes metabolic reprogramming of glucose and glutamine in cancer cells, ensuring rapid growth and proliferation of neoplastic cells." (PMID 35701309, 2022). "Further, aberrant activation of AKT/mTOR and WNT/β-catenin signaling are associated with therapy resistance across different cancer types, suggesting broad translatability for these markers and their underlying mechanisms of action." (PMID 35461372, 2022).
cancer (continued). "The class I PI3K, protein kinase B (PKB/AKT) and mechanistic target of rapamycin (mTOR) pathway (PAM pathway) display abnormal activation frequently in human cancer and plays a vital part in cell survival, proliferation, motility and metabolism." (PMID 36010585, 2022). "The AKT/mTOR signaling pathway can regulate cancer cell proliferation, growth, survival, and angiogenesis; its abnormal activation is also closely related to tumorigenesis and progression." (PMID 36429034, 2022). "The PI3K/AKT/mTOR signaling pathway plays a vital role in cancer which regulated cell proliferation, migration and invasion." (PMID 35812733, 2022). "One of the current approaches using mTOR inhibitors in cancer treatment involve their combination with other inhibitors that target critical metabolic pathways essential to cancer cell proliferation." (PMID 36135836, 2022). "The results of KEGG pathway enrichment analysis showed BZRAP1-AS1 correlated with tumor-associated signaling pathways including cell adhesion molecules (CAM), MAPK signaling pathway, mTOR signaling pathway, pathways in cancer." (PMID 36032951, 2022). "mTOR has been found to be abnormally over-activated in more than 70% of cancers such as breast, prostate, lung, liver, and renal carcinomas." (PMID 35788771, 2022). "Among them, the phosphoinositide 3-kinase (PI3K)/AKT/mTOR pathway is one of the most frequently activated in human cancers." (PMID 35311154, 2022). "Rapamycin targeting the mammalian target of rapamycin (mTOR) kinase can regulate autophagy and has therapeutic effects in patients with cancer." (PMID 36289714, 2022). "Phospho-S6 (pS6), a marker for the mTOR signaling pathway, is upregulated in HPV-associated cancers and has been extensively used as a biomarker for characterizing progressive neoplastic disease in multiple HPV transgenic mouse models." (PMID 36016373, 2022). "The dysregulation of mTOR signaling can result in many human diseases, including obesity, diabetes, fatty liver diseases, and various types of cancers." (PMID 35955521, 2022). "We found that the Wnt signaling pathway, VEGF signaling pathway, mTOR signaling pathway, ErbB signaling pathway, TGF-beta signaling pathway, and Hedgehog signaling pathway were associated with cancer." (PMID 36422982, 2022). "Compelling evidences reveal that dysregulation of PI3K/Akt/mTOR signaling contributes to the development of multiple cancers." (PMID 36319631, 2022). "The PI3K/mTOR axis is among the most frequently interrupted intracellular pathways in human cancers." (PMID 35614940, 2022). "As their representative, GDC-0941 has gained remarkable attention in cancer research over the past 10 years because of its 100-fold potency compared to other classes of dual PI3K/mTOR inhibitors." (PMID 36014303, 2022). "Such lipid metabolic alteration in cancers is critically regulated by the mammalian target of rapamycin mTOR, which is considered as a promising therapeutic target." (PMID 36438486, 2022). "The resulting aberrant activity of ALK contributes to cell growth and survival of cancer cells by induction of pathways such as the phosphoinositide 3-kinase/AKT/mammalian target of rapamycin (PI3K/AKT/mTOR) and RAS/mitogen activated protein kinase (MAPK)." (PMID 36551697, 2022). "Analysis of the KEGG pathway shows enrichment in the PI3K-Akt signaling pathway, mTOR signaling pathway, cellular senescence, and proteoglycans in cancer." (PMID 36532732, 2022). "mTOR is frequently deregulated in human cancer, and indeed mTOR inhibitors have been commonly used to treat human malignancies." (PMID 35538662, 2022). "Pharmacological research suggested that CA, an active ingredient extracted from Cinnamon, can inhibit the angiogenic activity of cancer by regulating the mTOR pathway‐mediated suppression of HIF‐1α expression." (PMID 34964259, 2022). "Meanwhile, several studies have suggested that the activation of mTOR signaling provides anti-cancer activity." (PMID 35406578, 2022).